FOXQ1 (forkhead box Q1)
Diseases named in the same sentence as FOXQ1 in open-access papers (continued):
Sharing a sentence is not in itself a finding about the gene and the disease.
cancer (continued). "Similarly, the JAK2/STAT3/miR-506-3p/FOXQ1 signaling pathway plays a key role in the interaction between immune cells and cancer cells in the CRC pathological microenvironment." (PMID 41347087, 2025). "Although these authors explored the function of FOXQ1 in the context of glucose metabolism, the findings may have important implications for cancer biology." (PMID 39777582, 2025). "Additionally, FOXQ1/NDRG1 (N-myc downstream-regulated gene 1) axis plays a key role between HCC and cancer-associated fibroblast (CAF) crosstalk." (PMID 41347087, 2025). "Several studies, discussed in the following sections, have outlined possible mechanisms that may drive the induction and accumulation of FOXQ1 in cancer." (PMID 39777582, 2025). "Besides transcriptional regulation, the levels of FOXQ1 in cancer cells are also determined by post-transcriptional and post-translational mechanisms." (PMID 39777582, 2025). "The molecular mechanisms that lead to FOXQ1 deregulation in cancer are incompletely understood." (PMID 38432629, 2024). "FOXQ1 in cancer cells can also be activated through oncogenic signaling pathways." (PMID 38839744, 2024). "Many studies have shown a correlation between FOXQ1 and cancer stem cells." (PMID 37875474, 2023). "Thus, MiR-937 directly targets FOXQ1 mRNA to operate as a cancer inhibitor in breast tumors and slow down the growth of the disease." (PMID 37626655, 2023). "In PC, FOXQ1 overexpression promotes cancer stem cell resistance to radiotherapy." (PMID 37875474, 2023). "Last, FOXQ1 was coexpressed with 47 immune-related genes in pan-cancer (p < 0.05)." (PMID 36118871, 2022). "FOXQ1 is known to act as an oncogene in many cancers, including BCa." (PMID 35396504, 2022). "Furthermore, previous studies have identified FOXQ1, PSEN1 and COL1A1 as the major molecular targets of miR-133 underlying its inhibitory role in EMT and cancer progression 23-26." (PMID 34335946, 2021). "FOXQ1 may promote β-catenin nuclear import indirectly via induction of annexin A2, but FOXQ1 also physically interacts with β-catenin in cancer cells." (PMID 34298659, 2021). "Higher expression of FOXQ1 was found in multiple cancers, including BC, suggesting that FOXQ1 may play an essential role associated with EMT." (PMID 34922601, 2021). "Elevated expression of FOXQ1 in HCT116-CSCs may be involved in regulation of expression pattern of genes which determine the characteristics of cancer stem cells." (PMID 32592372, 2020). "Furthermore, FOXQ1 has been shown to be a regulator of cancer invasion and metastasis in CRC and a modulator of Twist1 expression." (PMID 33330033, 2020). "Some studies have also unveiled an emerging role of FOXQ1 in modulating cancer stemness." (PMID 31853229, 2019). "Among them, FoxQ1 plays an important role in the invasion and metastasis of many cancers." (PMID 30927925, 2019). "Suppression of FOXQ1 inhibits cell proliferation, motility/invasion, and epithelial-mesenchymal transition phenotypes in cancer cells; a similar effect could be predicted in the breast of P women." (PMID 30922380, 2019). "Moreover, miR-4319 impeded cell proliferation, accelerated apoptosis, inhibited epithelial-mesenchymal transition and prevented cancer stemness of HCC through targeting FOXQ1." (PMID 31853229, 2019). "Notably, our study also found a novel reciprocal activation between cancer cells and TAMs that FoxQ1 expression in CRC cells co-cultured with TAMs promoted macrophage attraction in a CCL2-dependent manner." (PMID 30927925, 2019).
cancer (continued). "Additionally, upregulation of FOXQ1 is found in a large host of cancer types, possibly to regulate cell proliferation and invasion, including breast, colorectal, pancreatic, gastric, bladder, liver, lung, ovarian, and glioma." (PMID 29534099, 2018). "In view of the positive effect of FOXQ1 on the proliferation and metastasis of cancer cells, we speculated that FOXQ1 might also be involved in cellular senescence." (PMID 28726780, 2017). "Our findings may allow more effective approaches to the cancer treatment by inhibiting the expression of FOXQ1 and inducing cell senescence." (PMID 28726780, 2017). "Therefore, we curiously wanted to know the expression profile of FOXQ1 in cancer cells and its role in the cancer development." (PMID 28726780, 2017). "Moreover, our functional studies revealed that expression of FOXQ1 promoted cancer cell aggressiveness, and overexpression of FOXQ1 was involved in PDAC pathogenesis." (PMID 29050264, 2017). "In mammals, FOXQ1 is expressed both in embryos and a variety of adult tissues, is required for normal embryonic development, and has a recently discovered role in controlling epithelial-mesenchymal transition in human cancer metastasis." (PMID 25402455, 2014). "High expression of FoxQ1 has been associated with several cancers including non-small cell lung cancer (NSCLC), but its role in the development of NSCLC is not clear." (PMID 25356753, 2014). "FOXQ1, formerly known as HNF-3/forkhead homolog 1 (HFH1), belongs to a member of the forkhead transcription factor family, which are expressed in different tissues and play important roles in development, metabolism, cancer and aging." (PMID 22761930, 2012). "Thus, targeting FOXQ1 mRNA may be an alternative approach for inhibiting FOXQ1, at least in cancers with high HuR levels." (PMID 39777582, 2025). "Likewise, FOXQ1 is over-expressed in NSCLC cancer tissue compared with adjacent tissue." (PMID 41347087, 2025). "Thus, future in-depth studies on FOXQ1 functions may confirm its potential as a key marker of cancer diagnosis and therapy in the future." (PMID 41347087, 2025). "Additionally, FOXQ1 helps cancer stem cells regenerate themselves." (PMID 37626655, 2023). "Indeed, Foxq1 has been reported to downregulate the expression of muscle cell-specific genes by repressing the activity of corresponding promoters, and it played an antiapoptotic role in cancer tissue." (PMID 35677564, 2022). "Thus, they function as cancer-promoting genes, such as FOXQ1, PHLDA2, LPCAT2, AP1S3, and EPS8." (PMID 32977589, 2020). "Moreover, the miR-4319/FOXQ1 cascade may be a novel target via dampening cancer stem traits to ameliorate heterogeneity and improve the treatment outcomes of HCC." (PMID 31853229, 2019). "Hence, with the connection of EMT to disease progression in cancer pathology, our study might open up a novel perspective for future cancer therapy through modulation of cellular FoxQ1 activities." (PMID 25356753, 2014). "Therefore, FoxQ1 may play a key role in multiple drug resistance in human cancer and this likely occurs via multiple mechanisms." (PMID 25356753, 2014). "Additionally, FoxQ1 might be associated with resistance to conventional chemotherapy and downregulation of FoxQ1 may increase the sensitivity of chemotherapeutic reagents, with important implications in cancer progression and treatment." (PMID 25356753, 2014). "miR-4319 is a post-transcriptional regulator that directly dampens the expression of FOXQ1 to decrease cell proliferation, inhibit EMT, accelerate apoptosis, and prevent cancer stemness in HCC." (PMID 41347087, 2025). "Moreover, immune cells may control FOXQ1 levels in cancer cells as well." (PMID 39777582, 2025). "Thus, FOXQ1 may reinforce the EMT of cancer cells by inactivating tumour suppressor proteins." (PMID 39777582, 2025).
cancer (continued). "Moreover, FOXQ1 induction promoted other features typically associated with EMT, including the formation of remote metastases in mouse xenograft models, resistance to apoptosis caused by chemotherapeutic drugs, and the increased expression of cancer stem cell markers." (PMID 39777582, 2025). "Analysis of these transcriptional programs supports that FOXQ1 broadly controls cell migration and differentiation, consistent with its role in the EMT of cancer cells." (PMID 39777582, 2025). "In this article, I review the functions of the transcription factor FOXQ1, which has emerged as another FOX protein with major functions in cancers." (PMID 39777582, 2025). "FOXQ1 has been shown to promote epithelial-to-mesenchymal transition (EMT) and metastasis and to increase the resistance of cancer cells to chemotherapeutic drugs." (PMID 38432629, 2024). "FOXQ1 also plays a significant role in the biological processes that contribute to malignancy, including invasion, apoptosis, and EMT in diverse cancers, including breast cancer, rectal cancer, and intrahepatic cholangiocarcinoma." (PMID 37875474, 2023). "Indeed, FOXQ1 has been found to be overexpressed in variety of human cancers in digestive organs, such as liver, pancreas, and gastrointestinal tracts, where it could enhance tumorigenicity by inducing epithelial-mesenchymal transition, regulating cell cycle, and promoting cell proliferation." (PMID 37516739, 2023). "HFH1 (Forkhead box Q1, FOXQ1) has been reported to mediate epithelial-mesenchymal transition in various human cancers." (PMID 36978091, 2023). "Specifically, FOXQ1 has been observed to increase metastatic competence and drug resistance through triggering EMT in carcinoma cells." (PMID 37762215, 2023). "Forkhead box transcription factor, FOXQ1 is reported to promote epithelial-mesenchymal transition (EMT) and cancer metastasis." (PMID 36319643, 2022). "The other 11 up-regulated genes, such as FOXQ1, MMP7, MMP11, andCDH3, have been reported in previous cancer-related studies." (PMID 36434686, 2022). "However, the specific expression patterns and functions of FOXQ1 in pan-cancer remain unclear." (PMID 36118871, 2022). "A slight increase of IFI27, FOXQ1, PRF1, and SLC2A3 genes in CSCs probably implicate in phenotypes of cancer stem cells that were often quiescent, but being able to exhibit their chemoresistant properties." (PMID 32592372, 2020). "IHC results showed that the expression of FOXQ1, Twist1, and CCL2 in CRC tissues was significantly higher than that in para-carcinoma tissues." (PMID 33330033, 2020). "Similar studies reported that upregulation of FOXQ1 triggered EMT and contributed to metastasis and chemoresistance in several cancers." (PMID 29050264, 2017). "The studies have also described a key role for another member of the FOX family, namely forkhead box Q1 (FOXQ1), in regulating EMT and aggressiveness in some human cancers." (PMID 28580309, 2017). "Recently, the Forkhead transcription factor family, FOXQ1 and FOXM1 induce EMT and aggressiveness in human cancer." (PMID 27223064, 2016). "Previous studies have described a key role for forkhead box Q1 (FoxQ1) in regulating EMT and aggressiveness in human cancer." (PMID 22761930, 2012). "These authors attributed the effect of FOXQ1 to the regulation of SIRT1 expression, which may promote cancer cell stemness and radioresistance via the activation of the transcription co-factor β-catenin." (PMID 39777582, 2025). "Although the expressions of FOXP1 and FOXQ1 mRNA were increased in cancer tissue, the difference was not statistically significant (P > .05)." (PMID 38608123, 2024). "Likewise, TAMs conditioned by CRC notably elevate IL-6 secretion, activating the Jak2/STAT3 pathway and indirectly boosting forkhead box Q1 (FoxQ1) expression in cancer, thus reinforcing EMT and cancer stem cell attributes." (PMID 39286635, 2024).
cancer (continued). "FOXQ1 promotes EMT and metastasis in various carcinomas and may be a therapeutic target in, for example, breast and CRC." (PMID 38432629, 2024). "This analysis validated the identification of genes that could be specific to cancer biology, such as IL7R, JUN, NR3C1 in Ba/Sq subtype, NPAS2, FOXQ1, GRHL3 in Luminal samples, or CDKN2C, FOXJ1, MEIS2, FGFR3 in both subtypes." (PMID 36944729, 2023). "Furthermore, expression of miR-133 has been frequently linked to reduced cell proliferation and diminished invasive ability of cancer cells via downregulation of EGFR, FOXC1, FOXQ1 and PSEN114, 22-24." (PMID 34335946, 2021). "Since FOXQ1 contributes to cancer stem traits and tumourigenesis in HCC, we aimed to investigate whether FOXQ1 mediated the biological effects of miR-4319 in HCC." (PMID 31853229, 2019). "Additionally, overexpression of FOXQ1 and ANLN has been shown to promote cancer cell aggressiveness and is involved in PDAC pathogenesis." (PMID 29988949, 2018). "FoxQ1 expression was 3.75-fold higher on average in the cancer samples than in non-malignant tissues." (PMID 22761930, 2012). "To further confirm the FOXQ1-DDR2 or SNAI1-DDR2 axis in cancer cells, we knocked down the FOXQ1 gene in Hs.578t cells, and the SNAIL1 gene in MDA MB157 cells since each of these cell lines displayed high expression of either FOXQ1 or SNAIL1 with comparatively low expression of the other." (PMID 36713812, 2022). "However, the precise mode by which FOXQ1 and FOXJ1 activate Wnt signaling, and whether this function is relevant for their role in cancer biology, requires further investigation." (PMID 34298659, 2021). "Moreover, FOXQ1 is also known as a critical transcription factor that regulates epithelial-mesenchymal transition (EMT), a developmental process that is often activated during cancer invasion and metastasis." (PMID 23203039, 2012). "Thus, it is conceivable that FOXQ1 has additional roles in non-epithelial cells that may be relevant for cancer biology." (PMID 39777582, 2025). "Previous studies suggest that FOXQ1 induction may be driven by various mitogenic signaling pathways, including Wnt/β-catenin, YAP/TAZ, and FGFR1/ERK2 signaling; however, it is unlikely that these observations can sufficiently account for the increase in FOXQ1 levels across different cancer types." (PMID 38432629, 2024).
adenocarcinoma (4 papers, 2012 to 2017). A common cancer characterized by the presence of malignant glandular cells. "The average fold-changefor FOXC2 and FOXQ1 expression levels ingastric adenocarcinoma samples was 3.076(P=0.045) and 2.622 (P=0.03) respectively." (PMID 28580309, 2017). "Of the 152 predicted gene targets in mouse and human genomes, four were significantly regulated in laser dissected lung dysplasia (AZIN1, CHST1, CRISPLD2 and FOXQ1) while 11 genes were significantly regulated in laser-dissected adenocarcinomas." (PMID 24265725, 2013).
digestive system tumors (1 paper, 2024). "It has been reported that 17 genes play a key role in digestive system tumors, of which three are in the FOX family (FOXD1, FOXM1, and FOXQ1)." (PMID 38839744, 2024).
immune disease (1 paper, 2024). "OA is a typical age-related immune disease, and FOXQ1 is involved in the regulation of senescence-associated inflammation." (PMID 38503493, 2024).
neurological diseases (1 paper, 2025). "This work establishes FOXQ1 as an important regulator of brain endothelial metabolism and provides new insights into the molecular basis of cerebrovascular specialization, with implications for understanding vascular dysfunction in neurological diseases." (PMID 40884816, 2025).
FOXQ1 also shares sentences with these, for which no sentence is quoted: liver cancer (4 papers); infection (2); adrenocortical carcinoma (1); atherosclerosis (1); Axenfeld-Rieger syndrome type 3 (1); brain tumor (1); breast invasive carcinoma (1); Cerebral ischemia (1); cholangiocarcinoma (1); Conn's syndrome (1); diabetic nephropathy (1); diffuse large B-cell lymphoma (1); digestive system carcinoma (1); E. coli (1); endometrial cancer (1); essential thrombocythemia (1); head and neck squamous cell carcinoma (1); kidney cancer (1); kidney chromophobe (1); laryngeal carcinoma (1); leprosy (1); lung squamous cell carcinoma (1); lymphoid neoplasm (1); mesothelioma (1); myelofibrosis (1); neuroblastoma (1); osteoarthritis (1); osteoporosis (1); ovarian serous cystadenocarcinoma (1); pituitary adenoma (1).
A further 9 diseases each share a sentence with FOXQ1 in 1 paper.